CARM1 (coactivator associated arginine methyltransferase 1)
Diseases named in the same sentence as CARM1 in open-access papers (continued):
Sharing a sentence is not in itself a finding about the gene and the disease.
tumor (89 papers, 2010 to 2026). "Since aberrant overexpression or hyperactivation of CARM1 has been implicated in tumor progression, pharmacological inhibition of its activity has shown efficacy in preclinical models." (PMID 41152553, 2025). "These isoforms differ in structure and function: although CARM1-FL is associated with tumor-suppressive activity, CARM1-ΔE15 has been linked to oncogenic properties, altered enzymatic behavior and changes in subcellular localization." (PMID 41152553, 2025). "Through the process of enhancing small cell lung cancer (SCLC) tumor growth, coactivator-associated arginine methyltransferase 1 (CARM1) regulates arginine methylation of Smad7." (PMID 38841622, 2024). "Previous studies also indicated that CARM1 is associated with several crucial molecular processes, including RNA processing, transcriptional activation, tumor cell apoptosis, cell growth and progression." (PMID 35593475, 2022). "According to our findings, CARM1 displayed a significant association with tumor-infiltrating lymphocytes and played an important role in the TME." (PMID 34745258, 2021). "The GEPIA2 was used to integrate all of the top 100 genes, and TCGA tumor expression data were identified that were linked with the expression of CARM1." (PMID 34745258, 2021). "For example, arginine methylation of MDH1 induced by coactivator-associated arginine methyltransferase 1 (CARM1) suppresses tumor growth, but KRAS activation and oxidative stress relieve such inhibition." (PMID 32122374, 2020). "CARM1 expression is associated with poor prognostic factors such as young age of onset, high tumor grade, high proliferation, and increased P-cadherin expression." (PMID 26030442, 2015). "CARM1 was found to be to be expressed in 57% of triple negative cancers and was associated with high tumor grade." (PMID 24581278, 2014). "We found that levels of cytoplasmic CARM1 are distinct among tumor sub-types and increased levels are associated with ER-negative (ER-) status." (PMID 23663560, 2013). "Here, we report the associations of CARM1 expression and sub-cellular localization across 11 clinical variables, including tumor types, ethnic groups and overall survival." (PMID 23663560, 2013). "Furthermore, our results showed that defective autophagy process caused by CARM1 inhibition contributed to ER stress-related apoptosis, which also affected tumor growth." (PMID 35246137, 2022). "In addition, there was a significant association between CARM1 expression and the survival rate of tumor patients." (PMID 34745258, 2021). "Moreover, GCR and CARM1 pathway downregulation may be associated with tumor growth and survival, as these pathways are involved in endocrine regulation and metabolic diseases." (PMID 39354287, 2025). "Alterations in some epigenetic writers such as upregulation of PRMT1 and Coactivator-Associated Arginine Methyltransferase 1 (CARM1) are found in early tumours, suggesting that histone modifications and chromatin remodelling may act as epigenetic drivers at the initial stages of the disease." (PMID 35205419, 2022). "Notably, three of the ranked apoptosis-regulating genes (DAB227, DLC128,29, and NOXA30) are known tumor suppressors that are implicated in suppressing proliferation and promoting apoptosis, i.e., the phenotypes we observed when CARM1 was knocked out or EZH2 activity was inhibited with GSK126 (, 2)." (PMID 29434212, 2018). "The current study supports CARM1 as a therapeutic, druggable target for MM and introduces the novel concept of potentiation of the anti-tumor effects of IMiDs with CARM1 targeting." (PMID 40123976, 2025).
tumor (continued). "More importantly, the study for the first time proved that CARM1 inhibitor treatment significantly inhibits GC tumour growth both in vitro and in vivo, and synergises with autophagy inhibitors, presenting a promising therapeutic strategy." (PMID 39964832, 2025). "PRMT3 and CARM1(also known as PRMT4), being type I protein arginine methyltransferases, are key in controlling tumour progression by catalysing the mono‐methylation and asymmetric di‐methylation of both histone and non‐histone substrates." (PMID 39964832, 2025). "For example, CARM1 activates aerobic glycolysis and promotes tumor development by methylating the key glycolytic enzyme PKM2." (PMID 40016178, 2025). "Under hypoxic conditions, HIF1A is not only a binding partner of CARM1 but also plays a key role in its regulatory action, forming a positive feedback loop to enhance tumor cell adaptation to the hypoxic environment." (PMID 39995416, 2025). "To assess the effect of CARM1 on tumor metastasis in vivo, we intravenously injected HCC cells with or without CARM1 knockdown into the tail vein of nude mice." (PMID 40016178, 2025). "Conversely, within the active ASK1-p38/JNK apoptosis pathway (e.g., in the liver), where CARM1 is utilized to promote the clearance of damaged cells, it functions as a tumor suppressor gene." (PMID 41154773, 2025). "CARM1 inhibitors, such as EZM2302, resulted in anti-proliferative activity in MM cell lines in vitro and dose-dependent tumor growth inhibition in an MM tumor xenograft model in mice, thus revealing a dependency on CARM1 in MM." (PMID 40123976, 2025). "Consistent with our findings, a recent investigation revealed that CARM1 expression is notably correlated with survival and various clinical parameters, including alpha-fetoprotein levels, tumor size, satellite nodules, and microvascular invasion." (PMID 40016178, 2025). "Unlike its multifaceted, even contradictory “dual-sided” regulatory patterns in tumor and fibroblast cells, CARM1 exhibits high specificity in skeletal muscle, precisely focusing its function on glycogen metabolism pathways." (PMID 41488004, 2025). "They discovered that CARM1 facilitates tumour progression and metastasis through the methylation of the chromatin remodelling factor BAF155." (PMID 39964832, 2025). "CARM1 promotes tumor progression by methylating ACSL4 while inhibiting CARM1 can increase tumor cell sensitivity to ferroptosis, thereby promoting immunogenic cell death of tumor cells." (PMID 39273090, 2024). "While CARM1 regulates arginine methylation of Smad7 in tumor proliferation, rhArg and ARC are essential for MR in the arginine synthesis pathway." (PMID 38841622, 2024). "Recent studies have elucidated the profound significance of CARM1 in the regulation of tumor metabolism." (PMID 39266534, 2024). "6-AN treatment significantly inhibited xenograft tumor growth with cells having wild-type CARM1, similar to the effects of CARM1 silencing." (PMID 39266534, 2024). "CARM1 knockdown significantly reduced the number and diameter of tumor spheres, whereas its overexpression resulted in formation of more spheres with larger diameters, suggesting that CARM1 promotes stemness in TNBC." (PMID 38476024, 2024). "Using a large set of paired (normal/tumor) human BC tissues, a strong positive correlation between CARM1 and LSD1 was observed in the tumor samples." (PMID 37536629, 2023). "Together, these data argue that CARM1 regulates SCLC tumor growth via methylation of NFIB R388 and the subsequent recruitment of the methylation reader TRIM29." (PMID 36690626, 2023). "By using tumor weight as an indicator of tumor burden, we observed that the burden of orthotopic xenografts formed by CARM1-expressing A1847 cells was significantly reduced by CAY10566 treatment." (PMID 37377614, 2023). "CARM1 overexpression mouse models show that CARM1 retards tumor initiation, but promotes progression once tumors are initiated." (PMID 37536629, 2023).
tumor (continued). "Both the loss of CARM1 and the mutation of the CARM1 methylation site on NFIB in the TKO mouse model resulted in dramatically reduced lung tumor burden, as well as the levels of the tumor cell proliferation biomarker, phospho-H3." (PMID 36690626, 2023). "Inhibition of CARM1 can increase the sensitivity of tumor cells to ferroptosis inducers in vitro and in vivo." (PMID 37946697, 2023). "Remarkably, the observed effect in tumor suppression by CAY10566 treatment depends on CARM1 expression." (PMID 37377614, 2023). "The discovery of these new substrates has broadened the understanding of the mechanism of CARM1 in tumor progression." (PMID 37946697, 2023). "We examined the CARM1-NFIB regulatory module in SCLC by immunostaining human tumor samples for CARM1, NFIB and NFIBme2a." (PMID 36690626, 2023). "The results showed that overexpression of CARM1 substantially accentuated tumor growth compared to mice injected with CARM1-EV cells." (PMID 35246137, 2022). "Previous studies have mainly focused on the role of CARM1 as a coactivator in regulating tumor-related gene expression." (PMID 35246137, 2022). "The concrete mechanisms of CARM1 affecting tumor immune microenvironment still needs further experimental verification." (PMID 35033016, 2022). "In keeping with the xenograft tumor volumes, tumors from the nude mice injected with CARM1-overexpressing cells weighed more than the controls." (PMID 35246137, 2022). "In the tumor microenvironment, the inactivation of CARM1 can activate the DNA damage response of tumor cells, improve the TME, and promote the aggregation of innate immune cells." (PMID 35359945, 2022). "EZM2302 (a CARM1 inhibitor) and anti-PD-1 antibody significantly inhibited the immunosuppressive environment in vivo shaped by tumor growth in mice and reduced the efficacy of anti-PD-1 monotherapy in non-small cell lung cancer." (PMID 36713412, 2022). "Here, we counted the number of neoantigens in each tumor sample, and analyzed the relationship between them and the expression of CARM1." (PMID 35033016, 2022). "CARM1 is elevated in various tumors and exhibits a tumor-promoting role mainly as a transcriptional coactivator by methylating histones and non-histones." (PMID 35246137, 2022). "In contrast, CARM1 is downregulated in tumor relative to normal tissues in kidney Chromophobe (KICH) and kidney renal clear cell carcinoma (KIRC) (P < 0.001)." (PMID 35033016, 2022). "More importantly, treatment with a CARM1 inhibitor rescued the tumor-promoting effects of CARM1 both in vitro and in vivo." (PMID 35246137, 2022). "Because autophagy plays critical roles in tumor progression and CARM1 is known to play a regulatory role in autophagy, we analyzed the expression of autophagy markers in human GC tissues." (PMID 35246137, 2022). "In most cases, undifferentiated tumor cells express associated embryonic markers such as the OCT4, NANOG, SOX2, and CARM1 genes." (PMID 35274101, 2022). "IHC staining indicated that CARM1 expression was increased substantially in GC tissues in comparison with adjacent non-tumor tissues." (PMID 35246137, 2022). "Recently, CARM1 was discovered to be a negative regulator of tumor immunity that contributes to resistance to checkpoint blockade therapy." (PMID 35525959, 2022). "In the context of Neu-induced carcinogenesis, overexpression of PRMT1 and PRMT6 significantly accelerated breast tumor onset, while CARM1 increased tumor progression only at tumorigenesis." (PMID 35311114, 2022). "Overexpression of miR-424-5p inhibits the expression of CARM1 and increases the factors related to tumor progression and apoptosis, thus inhibiting tumor cell proliferation, migration and invasion and even improving the radiosensitivity of NSCLC." (PMID 35409396, 2022).
tumor (continued). "CARM1 was involved in immune modulation and played an important role in the tumor microenvironment (TME)." (PMID 34745258, 2021). "Recent studies have found that inhibition of CARM1 in both tumor cells and T cells produces beneficial antitumor effects." (PMID 34745258, 2021). "To evaluate the characteristics of CARM1 mRNA expression, we combined tumor and normal samples from TCGA and the GTEx databases, respectively." (PMID 34745258, 2021). "Transcriptome analysis revealed that platinum resistant tumors exhibited lower bulk tumor EZH2 expression with low CARM1 (and high MALAT1) co-expression." (PMID 34140011, 2021). "They showed that CARM1 inactivation by genetic knockout or by pharmacological inhibition in T cells enhanced anti-tumor T cell function." (PMID 34865122, 2021). "Using the HPA database to find CARM1 protein and mRNA expression profiles in human tissues, we investigated CARM1 expression in various tumor and normal tissues." (PMID 34745258, 2021). "On the basis of the GEO and TCGA databases, we first investigated the possible oncogenic functions of CARM1 in thirty-three tumor types." (PMID 34745258, 2021). "In contrast to these oncogenic functions, several reports have described the role of CARM1 as a tumor suppressor." (PMID 34006904, 2021). "Recently, Dr. Wucherpfennig's group reported that CARM1 genetic knockout or inhibition in T cells activates type I interferon response in tumor cells." (PMID 34865122, 2021). "Collectively, our results demonstrate that inhibition of BET or CARM1 significantly blocks tumor growth and metastasis in PDX models, possibly through inhibiting expression of SE-regulated oncogenes because this mechanism is shared between BRD4 and me-BAF155." (PMID 34865122, 2021). "To evaluate their in vivo effects, we injected HT29, c-Myc-KD, p300-KD, and CARM1-KD cells into nude mice to establish tumor xenografts." (PMID 32140074, 2020). "CARM1 inhibition has been shown to slow tumour growth in a multiple myeloma xenograft model, inhibit liver cancer cell proliferation and impair AML initiation and proliferation." (PMID 32011657, 2020). "To test CARM1 effects on tumor growth in vivo, we injected nude mice subcutaneously with control or CARM1 knockout MCF7 cells, and then treated with or without estrogen." (PMID 32206101, 2020). "Promising CARM1 inhibitors include EPZ022302/EZM2302 (a 6 nM CARM1 inhibitor with anti-tumour activity in vivo) and TP-064 (IC50 < 10 nM against CARM1 and >100-fold selective over other methyltransferases)." (PMID 32011657, 2020). "Together, we conclude that CARM1-mediated methylation of BAF155 drives a switch from BAF155 to EZH2 at the promoters of the BAF155/EZH2 target tumor suppressor genes." (PMID 29434212, 2018). "In contrast, our data clearly demonstrate that EZH2 inhibition can suppress the growth of CARM1-expressing tumors and improves survival of tumor bearing mice." (PMID 29434212, 2018). "The observed selectivity correlates with reactivation of EZH2 target tumor suppressor genes in a CARM1-dependent manner." (PMID 29434212, 2018). "Oral dosing of EZM2302 demonstrates dose-dependent in vivo CARM1 inhibition and anti-tumor activity in an MM xenograft model." (PMID 29269946, 2017). "Specifically, we find that the presence of EGFR and HER2 in specific tumor subtypes corresponds with distinct expression and localization of CARM1, suggesting potential interactions between CARM1 and these hormone receptors." (PMID 23663560, 2013). "Spearman correlation analysis was further preformed to confirm the correlation between nuclear CARM1 overexpression and patients’ age, tumor number and grade status, which were −0.197(p = 0.002), 0.231(p < 0.001) and 0.134(p = 0.035) respectively." (PMID 23915145, 2013). "These are insightful findings which cumulatively indicate distinct CARM1 activity and function among specific tumor subtypes." (PMID 23663560, 2013).
tumor (continued). "Cytoplasmic CARM1 expression was only correlated with the patients’ age at diagnosis (p = 0.041) and tumor grade (p = 0.019)." (PMID 23915145, 2013). "With the identification of PRMT6 and CARM1 as inhibitors of p21 and p27 a novel link between the methylation cycle and tumor suppression is pointed out." (PMID 22916108, 2012). "The CARM1 expression pattern was re-accessed with surgical or biopsied tumor specimens of patients with failed androgen ablation therapy and compared to tumors without PSA recurrence." (PMID 20462455, 2010). "To investigate whether CARM1 influences HCC tumor metastasis, we first examined whether CARM1 affects the migratory capacity of HCC cells by conducting a transwell assay." (PMID 40016178, 2025). "The contradictory effects of CARM1 may arise from the distinct metabolic environments of tumor cells, potentially involving different primary pathways of influence." (PMID 40016178, 2025). "In this study, we found that administering SGC2085 markedly inhibited the proliferation, migration, and invasion of HCC cells in vitro and strongly suppressed tumor growth in vivo, suggesting that targeting CARM1 may be a promising treatment for HCC." (PMID 40016178, 2025). "For instance, in tumor cells, CARM1 methylates Pyruvate Kinase M2 (PKM2)." (PMID 41488004, 2025). "The inhibition of CARM1 induces high antitumor efficacy in cytotoxic T-cells and tumor cells." (PMID 40016178, 2025). "However, the regulatory mechanisms of CARM1 expression and the role of CARM1 in regulating tumor metabolic pathways remain largely unclear." (PMID 39266534, 2024). "However, the mutual regulation between OGT and CARM1 during tumor progression needs to be further studied." (PMID 39715739, 2024). "Whether elevated CARM1 is involved in the regulation of tumor cell glucose metabolic reprogramming is unclear." (PMID 39266534, 2024). "Notably, the full-length CARM1 seems to exhibit tumor-suppressive function, while the short isoform (CARM1ΔE15) appears to have an oncogenic function in breast tumors." (PMID 38619752, 2024). "The involvement of CARM1-mediated GATAD2A methylation in tumor growth was also tested." (PMID 38676947, 2024). "There have been several reports on the regulation of CARM1 metabolism in tumour cells." (PMID 37649137, 2023). "We subsequently demonstrated that CARM1 moderates ferroptosis, thus facilitating tumor progression." (PMID 37946697, 2023). "Indeed, CARM1 loss or inhibition increases MLL3 chromatin recruitment and the activation of MLL3-dependent tumor suppressors." (PMID 37536629, 2023). "Subsequently, we validated the role of ACSL4 in CARM1‐induced tumor growth in vivo." (PMID 37946697, 2023). "In T cells, CARM1/PRMT4 inactivation enhances their anti-tumor activity." (PMID 36980950, 2023). "Thus, elevated Carm1 levels initially delay tumorigenesis, but then promote tumor growth once the tumor initiates in the mouse mammary gland." (PMID 37536629, 2023). "A gene enrichment analysis followed shortly, which implied that the role of CARM1 in tumor pathogenesis may be related to transcriptional imbalance and viral carcinogenesis." (PMID 35033016, 2022). "CDKN2AIP exhibits anti-tumor activity by interacting with CARM1 and eIF4β." (PMID 35593475, 2022). "The results show that the effect of CARM1 on tumor pathogenesis may be related to transcriptional misregulation and viral carcinogenesis." (PMID 35033016, 2022). "Here, analysis of the correlation between CARM1 and four methyltransferases (DNMT1, DNMT2, DNMT3a, DNMT3b) expression was conducted for each tumor to explore whether CARM1 expression is related to epigenetics." (PMID 35033016, 2022). "Given that CARM1 could promote GC tumor growth both in vitro and in vivo, we sought to investigate whether the CARM1 inhibitor (CARM1i) EZM2302 could exert a therapeutic efficacy." (PMID 35246137, 2022).